Y_RNA (Y RNA )
Gene: Miscellaneous RNA gene on chromosome 10 (92,272,147 to 92,272,250, reverse strand). Ensembl gene ENSG00000199881.
Homologues: Orthologues: chimpanzee Y_RNA (98% identical), macaque Y_RNA (90% identical). Paralogues in human: Y_RNA (81% identical), Y_RNA (80% identical), Y_RNA (79% identical), Y_RNA (78% identical), RNY1P5 (77% identical), Y_RNA (77% identical), Y_RNA (76% identical), RNY1 (75% identical), Y_RNA (75% identical), Y_RNA (74% identical), RNY1P1 (73% identical), RNY1P11 (73% identical), and 90 more.